CPT1A (carnitine palmitoyltransferase 1A)
Diseases named in the same sentence as CPT1A in open-access papers (continued):
Sharing a sentence is not in itself a finding about the gene and the disease.
cancer (156 papers, 2010 to 2026). A tumor composed of atypical neoplastic, often pleomorphic cells that invade other tissues. "CPT1A is upregulated in certain cancers and is associated with resistance to induction of apoptosis." (PMID 41235226, 2025). "Carnitine palmitoyltransferase 1A (CPT1A), a rate-limiting enzyme in fatty acid oxidation, has been implicated in the advancement of various cancers." (PMID 40016582, 2025). "Increasing evidence supported that CPT1A gene was associated with cancer cell metastasis and drug resistance." (PMID 39708716, 2025). "A previous study demonstrated that impaired CPT1A expression is associated with disrupted fatty acid oxidation in FDXR-depleted cancer cells." (PMID 40909793, 2025). "Based on the GEPIA database, TM7SF2 gene expression in cancer was significantly associated with CPT1A (P = 8.2 × 10−11, R = 0.36)." (PMID 38693136, 2024). "Overexpression of CPT1A has been consistently linked to adverse outcomes in a variety of cancers, including AML." (PMID 39703843, 2024). "The efforts to study the molecular mechanisms of CPT1A inhibition in disease intervention have increased in recent years due to the association with cancer." (PMID 37033619, 2023). "Previous research exploring the roles of CPT1s in other cancer types has revealed that CPT1s expression is positively associated with hypoxia, and CPT1A has been confirmed as the direct target of HIF1α." (PMID 37078750, 2023). "A prominent clinical feature of CPT1A mutations in humans is elevated free carnitine levels, increasing the rate of fatty acid metabolism and energy for cancer cells to use and increasing proliferation and mortality." (PMID 36735704, 2023). "Network analysis of the main cancer hallmarks and their associated pathways identified that CPT-1A clusters with genes in the autophagy, cell proliferation and DNA repair pathways in the context of gene overexpression." (PMID 36180554, 2022). "The high levels of CPT-1a in pancreatic ductal adenocarcinoma (PDAC) patients was associated with chemoresistance by rewiring cancer lipid metabolism to escape from energy stress." (PMID 35646898, 2022). "Although human studies looking at lipid oxidation in the setting of cancer are rare, several studies have focused on human populations carrying a mutation in the CPT1A (liver isoform) gene that confers some protection from PCa risk to arctic populations." (PMID 31142021, 2019). "Additionally, CPT1A overexpression has been associated with chemoresistance in multiple cancer types, and it has been observed that cancer cells surviving radiotherapy and chemotherapy enhance fatty acid oxidation through CPT1 and CPT2." (PMID 40867868, 2025). "A growing body of evidence associates CPT1A with the malignant progression of various cancers, for CPT1A may participate in the regulation of intracellular neutral lipid content, which is associated with the genesis of aggressive forms of cancers." (PMID 38693136, 2024). "CPT1A, acyl-CoA dehydrogenase, long-chain acyl-CoA synthetase, diacylglycerol choline phosphotransferase, and H+-transporting ATPase were associated with an elevated cancer risk." (PMID 39456670, 2024). "Sinomenine improves colitis-associated cancer by upregulating CPT1A." (PMID 39607749, 2024). "Carnitine Palmitoyl-Transferase1A (CPT1A) is the rate-limiting enzyme in the fatty acid β-oxidation, and its deficiency or abnormal regulation can result in diseases like metabolic disorders and various cancers." (PMID 37033619, 2023). "Further, BRAF overexpression and mutation is observed across cancers and targeting metabolic pathways, including CPT1a, may be an alternative approach to improving the response to treatment." (PMID 35565240, 2022). "Moreover, CPT1A lowers the risk of cancer recurrence and metastasis, reduces mortality, and offers prospective therapy options for clinical treatment if the effects of CPT1A on the lipid metabolism of cancer cells are inhibited." (PMID 41276823, 2025).
cancer (continued). "Among direct CPT1A inhibitors, etomoxir has been extensively studied in multiple cancer types, including prostate, breast, leukemia, and bladder cancers." (PMID 40867868, 2025). "CPT1A is the rate-limiting enzyme for FAO, and CPT1A-mediated FAO has been implicated in the progression of many cancers." (PMID 40016582, 2025). "Studies have shown that the expression of the FAO-related protein CPT is upregulated in cancer cells and that CPT1A plays an important role in the escape of cancer cells to cytotoxic T cells." (PMID 40002387, 2025). "The reason why research on SLC25A20 and the development of inhibitors have been behind the priority is that FAO of cancer cells was considered to be the same as that of normal cells, leading to CPT1A being targeted as the primary target." (PMID 40521210, 2025). "We discuss therapeutic implications of targeting the carnitine shuttle system, particularly CPT1A, to overcome ferroptosis resistance and enhance the efficacy of immunotherapy in various cancer types." (PMID 40867868, 2025). "Previous studies have already indicated the anti-apoptotic and anoikis resistance effects of CPT1A in mediating cancer cell survival and metastasis." (PMID 40718711, 2025). "A positive feedback loop exists between CPT1A and the oncogenic transcription factor c-Myc, which is crucial for maintaining cancer stem cell properties and preventing ferroptosis." (PMID 40867868, 2025). "Most of CEDGs like CCND1, ALDH3B1, MYEOV were frequently hypomethylated in cancer, while FGF3, FGF4, MRGPRF and CPT1A were hypermethylated in most cancers." (PMID 40478912, 2025). "Research has shown that CPT1A‐mediated succinylation modification plays an important role in various cancers." (PMID 40070041, 2025). "The upregulation of CPT1A, which is commonly observed in aggressive cancers, protects against ferroptosis by promoting FAO." (PMID 40867868, 2025). "For example, CPT1A is an appealing druggable target for cancer therapies because CPT1A is essential for the survival, proliferation, and drug resistance of cancer cells." (PMID 41276823, 2025). "Inhibitors of carnitine shuttle components such as CPT1A can sensitize cancer cells to ferroptosis inducers and enhance the efficacy of immunotherapy." (PMID 40867868, 2025). "Multiple malignant tumors are characterized by the significant overexpression of FAO enzymes Carnitine Palmitoyltransferase 1A (CPT1A), Carnitine Palmitoyltransferase 1B (CPT1B), and Carnitine Palmitoyltransferase-2 (CPT2)." (PMID 41164182, 2025). "Several genes altered during activation are approved or potential drug targets, including HMGCR, FADS1/2 and CPT1A, while others, such as FASN, CD36, and CTSD, are directly implicated in cancer-related processes." (PMID 40759959, 2025). "Among these, CPT1A has been widely studied and is frequently overexpressed in various types of cancers, including HNSCC." (PMID 40407216, 2025). "We observed that knockdown of the FAO gene, or inhibition by high glucose cultures, reduced ATP production by cancer cells significantly, which is consistent with previous observations of increased CPT1A expression in cancers." (PMID 40521210, 2025). "Targeting the CPT1A/c-Myc loop is considered a promising therapeutic strategy for overcoming ferroptosis resistance in cancer cells and enhancing the efficacy of immunotherapies." (PMID 40867868, 2025). "CD4+ T cell-derived interferon-γ induces CPT1A expression, conferring resistance to immune-mediated cytolytic killing in cancer cells." (PMID 41219902, 2025). "Our research revealed that CPT1A is a radiation sensitivity gene, contradicting previous literature, possibly due to differences in cancer types." (PMID 39607749, 2024). "Further exploration of other metabolic consequences of Nrf2 activation and inhibition, such as effects on nucleotide synthesis, is also essential for understanding cancer cell adaptation to metabolic stress, including the response to targeting Cpt1a." (PMID 39097623, 2024).
cancer (continued). "Meanwhile, compared with the Control group, pharmacological inhibition of CPT1A with etomoxir inhibited highly metastatic cancer cells lymph node metastasis in both vehicle and clodronate‐treated groups." (PMID 38520724, 2024). "The interaction between circTET2 and HNRNPC plays a crucial role in regulating the stability of carnitine palmitoyltransferase 1A, thereby impacting the lipid metabolism and proliferation of cancer cells." (PMID 38540406, 2024). "Targeting the inhibition of CPT1A provides a trajectory to enhance ferroptosis inducer-based cancer therapy." (PMID 39596904, 2024). "Increased Cpt1a activity enables cancer cells to utilize FAs as an energy source, bypassing the reliance on ErbB2 signaling for growth and survival." (PMID 39097623, 2024). "CPT1A also interacts with other key pathways and factors regulating gene expression and apoptosis in cancer cell." (PMID 39607749, 2024). "This contradicts previous findings that CPT1A overexpression accelerates ROS production by increasing fatty acid β-oxidation, thereby promoting ageing phenotypes or augmenting cancer cells’ oxidative defences." (PMID 39607749, 2024). "CPT1A is critical to cancer cell growth, survival, and drug resistance, making it an attractive target." (PMID 39607749, 2024). "With the in-depth study of epigenetic modification, researchers have found that CPT1A can also act as a succinylation-modifying enzyme to play a role in regulating the function of cancer cells through epigenetic modification of lysine." (PMID 39596847, 2024). "Etomoxir, a well-established CPT1A inhibitor, demonstrates notable antitumour effects across various cancer models." (PMID 38610991, 2024). "The expression of CPT1A is also activated by epigenetic control mechanisms, including various transcription factors or transcription coactivators, in different cancer types." (PMID 37803002, 2023). "Several studies have identified carnitine palmitoyl transferase 1 A (CPT1A) as a druggable target for various cancers, and targeting CPT1A has been shown to have anti-cancer effects." (PMID 37513899, 2023). "It will help to lower the risk of cancer recurrence and metastasis, reduce mortality, and offer prospective therapy options for clinical treatment if the effects of CPT1A on the lipid metabolism of cancer cells are inhibited." (PMID 37033619, 2023). "Metastasizing cancer cells rely on CPT1a-dependent palmitate oxidation to acetyl-CoA, which in turn serves as a substrate for the acetylation of p65 by KAT2a." (PMID 36732635, 2023). "There is evidence that CPT1A is crucial for metabolic adaptability in the development of cancer, and CPT1A inhibition slows the spread of cancer." (PMID 37033619, 2023). "Elevated CPT1A allows cancer cells to produce increasing levels of Ac-CoA through the mitochondrial FAO to promote activation of the β-catenin/Wnt signaling and cancer stem cell function." (PMID 36670988, 2023). "CPT1A helps the cancer cells to survive against stresses such as hypoxia, limited nutrition, and radiation." (PMID 37046804, 2023). "Targeted inhibition of CPT1A can be developed as an effective treatment strategy for cancers from a metabolic perspective." (PMID 37033619, 2023). "CPT1A is an appealing druggable target for cancer therapies since it is essential for the survival, proliferation, and drug resistance of cancer cells." (PMID 37033619, 2023). "CPT1A is the target gene of miR-328-3p, which promotes the invasion and metastasis of cancer cells by influencing cellular fatty acid metabolism and regulating cell stemness." (PMID 34045663, 2022). "Upregulation of FAO in CRC via overexpression of carnitine palmitoyl transferase 1A (CPT1A) decreases the ROS level and provides anoikis resistance [Cell death due to loss of adhesion, called anoikis, is a major hurdle for cancer cells during metastasis]." (PMID 36618350, 2022).
cancer (continued). "Taken together, these data imply that CPT-1A has a wide range of interactions with pathways involved in a range of cancer hallmarks, mediated at least in part by epigenetic mechanisms." (PMID 36180554, 2022). "To that end, we analyzed the expression of the rate-limiting enzyme, carnitine palmytoyltransferase 1A (CPT1A), in human tissues and cell lines representing different stages in the sequence from normal squamous esophagus to cancer." (PMID 36233047, 2022). "Recently, the function of CPT1A has drawn increasing attention with respect to cancer progression including metastasis and radiation-resistance." (PMID 34045663, 2022). "As shown, CD44, YAP and CPT1A RNA levels were all significantly increased in cancer tissues and were pairwise positively correlated." (PMID 35359362, 2022). "Studies with therapeutical interventions in fatty acid metabolic pathways, such as CPT1a inhibition in (haematological) cancers are ongoing and show promising results." (PMID 36100608, 2022). "Dysregulation of critical genes (such as ACACA, FASN, and CPT1A) in fatty acid metabolism, leading to an imbalance in fatty acid degradation and production, was considered as a potential metabolic marker for cancer cells." (PMID 35076025, 2022). "The results showed that the expression of CPT1A was higher in cancer tissue than adjacent normal tissue, and was higher in BC patients with metastasis than those without metastasis." (PMID 34045663, 2022). "Exposure of cancer cells to adipocytes, led to upregulation of CPT1A and FAO in tumor cells, which in turn promoted Wnt signaling and cancer stem cell properties." (PMID 35323656, 2022). "CPT1A was also overexpressed in many human tumors because of the uncontrolled proliferation of cancer cells." (PMID 36588740, 2022). "Carnitine palmitoyl transferase 1A (CPT1A) controls the rate-limiting step of fatty acid oxidation (FAO) which is increasing recognized as crucial metabolic signature of cancer." (PMID 33858374, 2021). "The energetic demands of cancer cells under this harsh environment also need to be satisfied to maintain growth, and CPT1A has emerged as a key player in cancer cell survival since it catalyzes the rate-limiting step for fat oxidation." (PMID 34944922, 2021). "Inhibition of CPT1A by both knockdown or utilization of its inhibitor etomoxir compromised cancer cell growth following reoxygenation." (PMID 34944922, 2021). "The high expression of CPT1A is related to apoptosis, proliferation and drug resistance among various cancers." (PMID 34213835, 2021). "In this study, we performed a comprehensive pan-cancer analysis on four well-known succinylation regulators (CPT1A, KAT2A, SIRT5, and SIRT7)." (PMID 33681201, 2021). "As an enzyme of the rate-limiting step of FAO, carnitine palmitoyl transferase1a (CPT1a) plays an important role in cancer metabolic adaptation." (PMID 33926484, 2021). "The results from the present study further support the therapeutic utility of targeting CPT1A expression in cancer cells." (PMID 34944922, 2021). "Suppressing CPT1A by etomoxir was demonstrated to decrease metastatic formation in vivo, which provides a potential target for cancer metastatic treatment." (PMID 35003369, 2021). "CPT1A has emerged as a key player in cancer cell survival, since it catalyzes the rate-limiting step for fat oxidation." (PMID 34944922, 2021). "During the last decade, carnitine palmitoyl transferase I (CPT1A) has been identified as a potential therapeutic target for a growing list of cancers." (PMID 33218188, 2020). "Because free fatty acids derived from adipocytes are in the form of long-chain fatty acids, upregulation of CPT1A allows the cancer cells to produce increasing levels of Ac-CoA via mitochondrial FAO to promote β-catenin activation and Wnt signaling." (PMID 32913185, 2020). "In accordance with these findings, we found an increased expression of PLIN2 and HILPDA, and reduced levels of CPT1A transcripts in cancer tissue." (PMID 33322148, 2020).
cancer (continued). "During the last decade, CPT1A has been identified as a potential therapeutic target for a growing list of cancers." (PMID 33218188, 2020). "In these cancers, CPT1A expression is increased, and/or its inhibition has been reported to have antitumor effects." (PMID 33218188, 2020). "Here we investigated if upregulation of CPT1A is required to mediate the effect of adipocytes on promoting cancer stem cell functions." (PMID 32913185, 2020). "Our study identifies CPT1A upregulation as a key metabolic alteration that cancer cells adapt to promote β-catenin acetylation and activation in an adipocyte-enriched TME." (PMID 32913185, 2020). "Studies focused on the role of lipid oxidation via CPT1A have brought attention to the role of lipid catabolism by cancer cells." (PMID 31142021, 2019). "Blocking CPT1a results in cancer cell death and decreased resistance to radiation and chemotherapeutic agents of cancer cells." (PMID 31315616, 2019). "Carnitine palmitoyltransferase 1A (CPT1a), which was upregulated in cancer cells, was also increased by NR6A1 knockdown." (PMID 31315616, 2019). "Recent studies have shown that CPT1A is strongly expressed in several cancers, including the hormone-dependent breast and prostate cancers." (PMID 31142021, 2019). "CPT1A is involved in the fatty acid oxidation pathway and has been proposed as a target of cancers such as nasopharyngeal and prostate carcinomas." (PMID 31699026, 2019). "The accumulation of lipids observed in CPT1A OE cells is also a characteristic of more aggressive cancers." (PMID 31547059, 2019). "Fasn is associated with cancer metabolism and was downregulated dramatically in SAHA/JQ1-treated cells, whereas Cpt1a and Cpt1b and the muscle differentiation factor Mef2c were elevated." (PMID 30382078, 2018). "Pharmacological inhibition of CPT1A results in impaired cancer cell proliferation in acute myeloid leukemia and intensive cytotoxicity in Burkitt’s lymphoma." (PMID 29445084, 2018). "An important role of FAO key enzyme, carnitine palmitoyl transferase 1a (CPT-1a) has been demonstrated in cancer cell survival in conditions of energy stress as it rewires the cancer cell metabolism." (PMID 28447025, 2017). "To understand the clinical significance of CPT1A suppression in ccRCC, we queried cancer gene expression databases for CPT1A levels in patient samples." (PMID 29176561, 2017). "Treatment of Tregs with etomoxir, a CPT-1a inhibitor resulted in differential suppression of Treg generation but not Th1 cells making etomoxir a promising metabolic modulator for cancer therapy." (PMID 28447025, 2017). "Previous studies of CPT1A in cancer have been restricted to pharmacological inhibitors such as etomoxir or its combination with inhibitors co-targeting other metabolic, oncogenic or survival cascades." (PMID 26716645, 2016). "To elucidate biological functions of CPT1A in cancer cells in a more specific manner, we used lentivirus-mediated shRNA to knockdown its expression in SKOV-3, Caov-3, OVCA-432 and OVCAR-3 that expressed highest levels of endogenous CPT1A." (PMID 26716645, 2016). "This is the first evidence that CPT1A positively contributes to the regulation of cancer cell motility." (PMID 22533991, 2012). "The identification of CPT1A suggests that managing lipid profiles may be critical for mitigating the "metabolic fuel" that accelerates cancer progression." (PMID 41976360, 2026). "Importantly, CPT1A knockdown in cells transfected with miR-365-3p almost abolished the ability of miR-365-3p to inhibit cancer xenograft growth." (PMID 40016582, 2025). "Targeting the CPT1A expression pathway seems like a promising cancer therapeutic strategy." (PMID 41219902, 2025).